IL13 (interleukin 13)
Diseases named in the same sentence as IL13 in open-access papers (continued):
Sharing a sentence is not in itself a finding about the gene and the disease.
Headache (3 papers, 2014 to 2026). Cephalgia, or pain sensed in various parts of the head, not confined to the area of distribution of any nerve. "TNF-α and IL-13 showed moderate positive correlation with headache." (PMID 25343623, 2014). "Regarding the central tendency measures, in the comparison of the crude median values of cytokines, we observed that patients with headache had higher median values of GROa, IFN-gamma, IL-10, IL-13, IL-15, IL-17a, IL-21, IL-22, IL-27 and IL-6." (PMID 34088273, 2021).
Hepatic steatosis (3 papers, 2016 to 2025). Steatosis is a term used to denote lipid accumulation within hepatocytes. "Accordingly, another study demonstrated that exogenous IL-25 administration protects against hepatic steatosis through IL-13-induced activation of STAT6." (PMID 41409600, 2025). "IL-13 has been shown as an independent predictor of the liver steatosis severity." (PMID 36544761, 2022). "IL-25 promotes hepatic macrophage differentiation towards the M2a phenotype, both in vivo and in vitro, via the IL-13/STAT6 pathway, alleviating HFD-induced hepatic steatosis." (PMID 41409600, 2025). "A differential expression of IL-13, G-CSF, CCL11, IL-6 and IL-4 among patients at different stages of hepatic steatosis, highlighted a possible role of an inflammatory response in the development of hepatic steatosis and fibrosis in CHB patients." (PMID 36544761, 2022).
immune deficiency (3 papers, 2017 to 2019). "al. have studiedimmunological factors including IL-4, IL-5, IL-13 and PGE2 in vaginal discharge in women withRVVC proposing that infected cases had a specificlocal immune deficiency in that area." (PMID 28868834, 2017). "A state of immune deficiency might therefore arise from IL-4Rα targeting as opposed to IL-13 targeting where Th2 responses are optimally elicited." (PMID 28827803, 2017).
interstitial lung disease (3 papers, 2009 to 2025). A diverse group of lung diseases that affect the lung parenchyma. "Our aim was to test whether both IL-33 and IL-13 are higher in patients with diffuse SSc and interstitial lung disease (SSc-ILD) compared to SSc patients without ILD and healthy controls." (PMID 35252259, 2022). "Therefore, our aim was to verify the preliminary hypothesis that both IL-33 and IL-13 are higher in patients with diffuse SSc and interstitial lung disease (SSc-ILD) compared both to SSc patients without ILD, as measured through pulmonary function tests (DLco, TLC, FVC), and to healthy controls." (PMID 35252259, 2022).
intestinal tumor (3 papers, 2016 to 2024). "They found that intestinal tumor development was markedly increased in Il13−/− compared with WT mice, which further indicates a pro-tumorigenic effect of IL-4 in CRC." (PMID 27148488, 2016). "Recent research has shown that IL-4 and IL-13 promote the function of M-MDSCs and inhibit anti-tumor immunity in intestinal tumors, suggesting IL-4 and IL-13 could be potential targets for improving CRC immunotherapy." (PMID 39262952, 2024). "S9D) and treated them with either a combination of anti-IL-4 and anti-IL-13 neutralizing antibodies (αIL-4/13Ab-ILC2-SNT), or isotype control antibody (conAb-ILC2-SNT), before adding them to purified intestinal tumor M-MDSCs or splenic M-MDSCs from Apc1322T/+ mice." (PMID 35658010, 2022).
knee osteoarthritis (3 papers, 2017 to 2025). "Similarly, in a sample of participants living with knee osteoarthritis, pain relief was mediated by changes in IL-1ß and IL-13." (PMID 40649738, 2025). "Also, plasma levels of the anti-inflammatory cytokines IL-4, IL-7, IL-10, and IL-13 seem to increase after exercise in healthy subjects and IL-10 also in patients with knee-osteoarthritis." (PMID 28243900, 2017).
latent infection (3 papers, 2012 to 2025). "To determine the relevant producers of type 2 cytokines during chronic, latent infection, we then infected Il4KN2/+ and Il13KN4/+ mice to report endogenous IL-4 and IL-13 production, respectively." (PMID 40568097, 2025). "In contrast, all Il4/Il13−/− mice survived the infection and had undetectable pulmonary fungal burdens at 140 dpi, suggesting that type 2 cytokines antagonize sterilizing immunity during latent infection." (PMID 40568097, 2025).
leprosy (3 papers, 2009 to 2024). Leprosy is a chronic infectious disease affecting primarily the skin and peripheral nervous system. "Another point that can help in understanding the role of IL-10 and IL-13 PB and MB leprosy and corroborate with our data, concerns the analysis of IL-9 levels in leprosy patients in this study." (PMID 38381878, 2024). "Likewise, other cytokine of profile regulatory the IL-13 was increased in the plasma of patients with PB leprosy." (PMID 38381878, 2024).
leukopenia (3 papers, 2015 to 2020). "The T allele in IL13 rs1800925 was associated with an increase in the risk of leukopenia (OR = 6.76, 95 % CI = 1.35–33.9, P = 0.020) and increased prevalence of any toxicity > grade 2 (OR = 1.75, 95 % CI = 1.06–2.88, P = 0.028)." (PMID 26387812, 2015). "Presence of the IL13 rs1800925 T allele was associated with an increased risk of leukopenia (OR = 6.76, 95 % CI = 1.35–33.9, P = 0.020) and also with development of any toxicity > grade 2 (OR = 1.75, 95 % CI = 1.06–2.88, P = 0.028)." (PMID 26387812, 2015). "We observed an increased risk of leukopenia in carriers of the variant allele of IL13 rs1800925C>T. Leukopenia is a common haematologic adverse event in sunitinib treatment of which the mechanism remains uncertain." (PMID 26387812, 2015). "T carriers of IL13 rs1800925 had an increased risk of leukopenia (OR = 6.76) and an increased risk of any toxicity > grade 2 (OR = 1.75)." (PMID 26387812, 2015).
lung squamous cell carcinoma (3 papers, 2022 to 2025). "Elevated IL-10, IL-13, and TERT levels and reduced MCP-1/MCAF levels are associated with lung squamous cell carcinoma." (PMID 40292253, 2025). "In our study, IL-13 emerged as a potential protective factor against lung squamous cell carcinoma, suggesting a complex interplay in its function, highly dependent on the cancer's pathobiological context and disease stage 54." (PMID 39132165, 2024).
Lymphadenopathy (3 papers, 2013 to 2022). Enlargement (swelling) of a lymph node. "In numerous cHL specimens increased levels of both pro- and anti-inflammatory cytokines and of IL13 and GM-CSF were observed compared to reactive lymphadenopathies." (PMID 25470820, 2014). "Similarly, IL-6 (P=0.0006), IL-10 (P=0.001), IL-12p40 (P=0.03), TNFα (P≤0.002) and chemokines MIP-1β (P<0.0001) and MCP-1 (P=0.002) (but not IL-1β, IL-13 and G-CSF) were significantly elevated in Tg mice at late stages of lymphadenopathy (Tg L) relative to WT controls." (PMID 23985023, 2013).
lymphopenia (3 papers, 2008 to 2021). Reduction in the number of lymphocytes. "Aside from lymphopenia, the impaired release of IL-12 and IL-13 by DCs may thus contribute to the increased susceptibility of Idelalisib-treated patients to CMV infection." (PMID 34173009, 2021). "Systemic immune aberrations in ALS patients include alterations in macrophage activation profiles, elevated levels of complement proteins in sera, increased IL-13 producing T cells and circulating neutrophils, lymphopenia with reduced number of CD2+ and CD8+ T cells." (PMID 18648532, 2008).
medulloblastoma (3 papers, 2002 to 2017). A malignant, invasive embryonal neoplasm arising from the cerebellum. "The cytotoxic activity of cpIL4-PE can be neutralized by either excess IL-4 or IL-13, indicating that IL-4R are related to IL-13R on medulloblastoma cell lines." (PMID 28752098, 2017). "The sensitivity of medulloblastoma cells to cpIL4-PE could be eliminated by concurrent incubation with IL-4 or IL-13, but not with IL-2." (PMID 11870521, 2002).
memory impairment (3 papers, 2016 to 2024). "Il-13 is expressed in neurons and IL-13 ko causes memory impairment." (PMID 36639371, 2023). "Males: ↑ monokine expression (IFN-γ, TNF-α, IL-10 and IL-13) and memory impairment compared to females." (PMID 39126053, 2024).
microcephaly (3 papers, 2018 to 2023). A congenital or acquired developmental disorder in which the circumference of the head is smaller than normal for the person's age and sex. "Gene expression quantified by qPCR in whole blood samples showed an increase in IFNγ and IL-13 transcripts in children affected with microcephaly compared to the control group." (PMID 37766239, 2023). "A polyfunctional immune activation associated with increased CCL2, CXCL10, IL-6, IL-8, VEGF, and G-CSF levels but decreased levels of IL-13 was also described in the amniotic fluid of ZIKV-positive pregnant women whose infants had microcephaly." (PMID 29768624, 2018). "In this study, we demonstrate that children with microcephaly due to CZS present dysregulation of antagonistic inflammatory mediators, characterized by increased mRNA expression of IFNγ and IL-13." (PMID 37766239, 2023).
multiple myeloma (3 papers, 2021 to 2026). "Pairwise protein analysis confirmed cosecretion of IL-1β and IL-6 in macrophages stimulated with IL-4/IL-13, which were identified as part of a critical pathway in multiple myeloma before." (PMID 42292686, 2026). "Th17 cells can also stimulate the secretion of IL-1α, IL-13, IL-17, and IL-23, as well as promoting myeloma cell growth, colony formation, and growth of xenografts in mouse models of MM20." (PMID 36224246, 2022). "At baseline, most Th2 cytokines (i.e., IL-4, IL-5, IL-6, and IL-13) were elevated in the multiple myeloma patients, compared to healthy controls, and most patients had a Th1/Th2 score <1.0, suggesting Th2 dominance." (PMID 34239993, 2021).
neuroblastoma (3 papers, 2019 to 2024). Neuroblastoma (NB) is the most common solid, extracranial childhood tumor. "Neuroprotective effects of IL-13 were investigated using different cell viability assays in murine and human neuroblastoma cell lines, human neurospheroids, as well as murine organotypic brain slice cultures." (PMID 35488301, 2022). "In both murine and human neuroblastoma cell lines, neither pre- nor co-treatment with IL-13 protected against NO-induced cell death." (PMID 35488301, 2022). "Consistent with our previous findings, a lack of IL‐13 enhanced lung injury following Nb infection." (PMID 39606183, 2024). "Whereas direct neuroprotective effects of IL-13 on murine and human neuroblastoma cell lines or human neurospheroid cultures were absent, IL-13 rescued murine organotypic brain slices from cell death, probably by indirectly modulating the Mφ/microglia responses." (PMID 35488301, 2022).
neutropenia (3 papers, 2005 to 2020). A decrease in the number of neutrophils found in the blood. "In this study, we evaluated the role of neutrophilic and eosinophilic inflammation by pretreatment with cyclophosphamide inducing neutropenia and the association of IL-13 by pretreatment with dexamethasone suppressing IL-13 gene expression." (PMID 15829015, 2005). "In contrast, Th2 cytokine levels such as IL-4 and IL-13 were not modified by neutropenia." (PMID 26020515, 2015).
ocular toxoplasmosis (3 papers, 2013 to 2020). Ocular toxoplasmosis is an infection in the eye caused by the parasite, Toxoplasm a gondii. "These molecular observations are in keeping with results of intraocular cytokinome profiling in South American patients, which identify IL-13 as a biomarker for severe ocular toxoplasmosis." (PMID 31547203, 2019).
onchocerciasis (3 papers, 2020 to 2021). Onchocerciasis is a form of filariasis, caused by the parasitic worm Onchocerca volvulus, transmitted by the black fly. "Given that GWAS studies of onchocerciasis show association of IL‐13 polymorphisms with the development of pathology, an investigation of the role of IL‐13 is warranted." (PMID 32145033, 2020).
oral squamous cell carcinoma (3 papers, 2020 to 2022). "On the other hand, these two anti-inflammatory cytokines, IL-10 and IL-13, have been identified as elevated in oral squamous cell carcinoma." (PMID 31973090, 2020).
osteosarcoma (3 papers, 2024 to 2025). A usually aggressive malignant bone-forming mesenchymal neoplasm, predominantly affecting adolescents and young adults. "To examine whether endogenous expression of IL13RA1-LOR1a can affect the ability of the cells to sense IL-4 or IL-13, we targeted its expression in U2OS osteosarcoma cells, which respond to stimulation by up-regulating CCL26." (PMID 40614216, 2025).
pancreatitis (3 papers, 2009 to 2021). Inflammation of the pancreas. "Although cellular sources of IL-33 are different in IBD and pancreatitis, IL-33 mediates tissue fibrosis in both disorders through induction of pro-fibrogenic factors such as IL-13." (PMID 34759844, 2021). "We have evaluated this possibility in vitro by treating pancreatitis-activated peritoneal macrophages with a mixture of IL-4 and IL-13." (PMID 19646232, 2009). "With this purpose we treated in vitro peritoneal macrophages obtained 18 hours after inducing pancreatitis, with IL-4 plus IL-13, which are known to induce a M2 phenotype in macrophages." (PMID 19646232, 2009). "Results indicate that activated peritoneal macrophages obtained during pancreatitis could be re-directed to M2 phenotype by the effect of IL-4 and IL-13 treatment." (PMID 19646232, 2009).
papilloma (3 papers, 2013 to 2016). A benign epithelial neoplasm that projects above the surrounding epithelial surface and consists of villous or arborescent outgrowths of fibrovascular stroma. "Treatment with IL-13-PE was then initiated four weeks from the day tumor induction began, since papillomas and early carcinomas generally start to appear at this time in the Tgfbr1/Pten 2cKO mouse." (PMID 23421960, 2013). "A similar, perhaps less pronounced increase in papilloma incidence was observed for IL-13−/− mice as had been observed for IL-4Rα−/− mice, suggesting that IL-13 signaling via IL-4Rα is responsible for the protective effect." (PMID 24403255, 2013). "Indeed, IL-13−/− mice developed more papillomas after exposure to DMBA/TPA than their heterozygous IL-13-competent littermate controls." (PMID 24403255, 2013). "Because we detected an increase in papilloma incidence in IL-4Rα−/− compared to IL-4−/− mice, we reasoned that IL-13 as the second ligand for IL-4Rα might have been responsible for this difference." (PMID 24403255, 2013). "The fact that RAG2−/−/IL-4Rα−/− double-knockout mice and RAG2+/+/IL-4Rα−/− both showed increased papilloma incidence suggests that IL-13 signaling neither in T cells, nor in B cells was the main reason for enhanced papilloma incidence." (PMID 24403255, 2013). "We found that IL-4Rα−/− but not IL-4−/− mice have enhanced papilloma formation, suggesting that IL-13 may be involved." (PMID 24403255, 2013).
pemphigus (3 papers, 2016 to 2019). Pemphigus is a group of rare autoimmune diseases that cause blistering of the skin and mucous membranes (mouth, nose, throat, eyes, and genitals).This conditioncan occur at any age, but often strikes people in middle or older age. "Upregulation of the Th2 cytokines IL-4, IL-5, IL-10, and IL-13 has been described in pemphigus patients." (PMID 27304671, 2016).
pneumococcal infection (3 papers, 2017 to 2022). Infections with bacteria of the species streptococcus pneumoniae. "As expected, the classic type-2 cytokines IL4, IL5, and IL-13 were increased in the lungs of HDM-exposed mice, and pneumococcal infection did not alter their respective levels." (PMID 35273509, 2022).
prion disease (3 papers, 2013 to 2026). A transmissible disease that is caused by a protein that is able to induce abnormal folding of normal cellular proteins, leading to characteristic spongiform brain changes, which are associated with neuronal loss without an inflammatory response. "Conversely, TNF-α, IL-4, IL-6, IL-12(p40), IL-12(p35), IL-13, and transforming growth factor-β1 are probably not pathogenic in prion disease because knockout of these cytokines did not change the disease course of prion-inoculated mice." (PMID 24219883, 2013).
Salmonella Infections (3 papers, 2012 to 2021). Infections with bacteria of the genus SALMONELLA. "Additional studies are needed to understand the role of IL-13 during Salmonella infection, and the mechanisms by which Ara4N-deficient S. Typhimurium is attenuated by oral, but not intraperitoneal infection." (PMID 23166721, 2012). "In contrast to our Salmonella infection model, induction of Arg1 in L. major infection in BALB/c mice was driven by a strong Th2 response releasing IL-4 and IL-13 and not by the pathogen itself." (PMID 34359992, 2021).
sarcopenia (3 papers, 2020 to 2025). Progressive decline in muscle mass due to aging which results in decreased functional capacity of muscles. "The average levels of the four proinflammatory cytokines, including IL-1β, IL-6, IL-15, and TNF-α, were significantly increased in sarcopenia patients compared to those in young/healthy volunteers, while the concentrations of two other cytokines, IL-4 and IL-13, were not changed." (PMID 32226296, 2020).
SARS-CoV infection (3 papers, 2020 to 2022). "Previous studies have demonstrated that during the early stage of SARS-CoV infection – usually up to 7 days post-symptoms – Th2 predominant cytokine profile characterized with increased secretion of TGFβ and IL‐13 is apparent." (PMID 33092458, 2020).
Sm (3 papers, 2019 to 2025). "There were significant positive associations between Sm infection and PPD-specific cytokine and antibody responses, as observed for PPD-specific IL-13 (aGMR 1.75 [1.19, 2.56], p = .007) and IgG4 responses (aGMR 1.12 [1.00, 1.26], p = .046)." (PMID 32387542, 2020). "Furthermore, a recent study showed that IL-33 needs to synergize with two other cytokine alarmins, thymic stromal lymphopoietin (TSLP) and IL-25, to induce IL-4/IL-13-dependent inflammation and fibrosis after Sm infection." (PMID 31200771, 2019). "Indeed, additional germline variants in KIT and in genes encoding for cytokines or their receptors (e.g., IL13, IL6, IL6R, IL31, IL4R), as well as increased copy numbers of the TPSAB1 gene encoding for α‐tryptase, have been increasingly recognized as associated with systemic mastocytosis in adults." (PMID 41177946, 2025).
Splenomegaly (3 papers, 2009 to 2013). Abnormal increased size of the spleen. "IL-33 plays a major role in Th2 responses by inducing Th2 cytokines IL-4, IL-5, IL-13, splenomegaly, eosinophilia, and allergy." (PMID 23112799, 2012). "Indeed, Tir8/Sigirr-deficient mice showed hyper responsiveness to IL-33 with increased serum levels of IL-5 and IL-13, splenomegaly, lung inflammation, and exacerbated Th2 responses in OVA-induced allergic pulmonary inflammation." (PMID 23112799, 2012). "Among children who were S. mansonipositive, levels of IL-13 were significantly higher for children with moderate splenomegaly compared with those with no splenomegaly." (PMID 19149774, 2009).
squamous cell carcinoma (3 papers, 2012 to 2024). A carcinoma arising from squamous epithelial cells. "IL-13-PE was administered to the mice as they first started to succumb to tumor-associated mortality from the developing squamous cell carcinomas." (PMID 23421960, 2013). "We have previously shown that cultured cells derived from the periorbital and perianal squamous cell carcinomas collected from another TGFβRI conditional knockout model can also express IL-13Rα2 and are sensitive to IL-13-PE treatment." (PMID 23421960, 2013).